INS (insulin)
Diseases named in the same sentence as INS in open-access papers (continued):
Sharing a sentence is not in itself a finding about the gene and the disease.
type 1 diabetes (continued). "A small double-blind placebo-controlled crossover trial conducted in France in the mid 1980s reported an improvement in euglycaemic–hyperinsulinaemic clamp-assessed insulin sensitivity when metformin was added to insulin therapy for 7 days in ten non-obese people with type 1 diabetes." (PMID 28770327, 2017). "Glucose-fructose co-ingestion may have a beneficial impact on fuel metabolism in exercising individuals with type 1 diabetes without insulin adjustment, by increasing fat oxidation whilst sparing glycogen." (PMID 28230765, 2017). "Although these technologies have been shown to reduce the incidence of severe hypoglycaemic events, including those leading to hypoglycaemic seizure or coma, they do not address the issue of variability in insulin requirements, which remains an unmet need in patients with type 1 diabetes." (PMID 28094136, 2017). "Of patients misclassified by the UK guidelines’ clinical criteria in comparison with the gold standard (n = 87), most (n = 57, 66%) were misclassified as having type 1 diabetes and were producing substantial endogenous insulin ≥5 years post diagnosis (data not shown)." (PMID 27080317, 2016). "Maternal and foetal fructosamine was not different between groups (data not shown) and interpretation of maternal insulin and C-peptide levels were compromised by the presence of subjects with type 1 diabetes in the pre-gestational diabetes group (data not shown)." (PMID 27736899, 2016). "Furthermore, ATG does not reverse type 1 diabetes in the acute virally induced rat insulin promoter-lymphocytic choriomeningitis virus (RIP-LCMV) model." (PMID 26911290, 2016). "However, because SGLT2 inhibitors have a mechanism of action that does not require the presence of endogenous insulin, these drugs should also be efficacious in type 1 diabetes where endogenous insulin production is greatly reduced or absent." (PMID 25785209, 2015). "Since our in vitro experiments suggest that ADAM10 may play a role in insulin-stimulated RAGE shedding, we have measured serum ADAM10 in a group of type 1 diabetic patients and healthy controls, and evaluated the relationship between ADAM10 and the various soluble RAGE isoforms." (PMID 26325204, 2015). "In autoimmune type 1 diabetes mellitus (T1D), auto-reactive clones of CD4+ and CD8+ T lymphocytes in the periphery evolve into pancreas-infiltrating T lymphocytes (PILs), which destroy insulin-producing beta-cells through inflammatory insulitis." (PMID 26606254, 2015). "In adult series of type I diabetes patients, the prevalence of both severe (10–30%) and moderate (22–56%) PEI seems higher than in children, possibly suggesting that exocrine pancreatic function decreases in parallel with the duration of disease and the increase in insulin requirement." (PMID 25892991, 2015). "We speculate that if insulin (especially exogenous insulin) plays a role in regulating the expression and shedding of RAGE, this might partly explains why total sRAGE levels are increased in majority of the studies in type 1 diabetes." (PMID 26325204, 2015). "However, such options are not yet available in the market and insulin remains the mainstay of treatment of type 1 diabetes." (PMID 25866533, 2015). "Furthermore, all patients with non-insulin-dependent diabetes and with moderate PEI (fecal elastase concentrations <200 μg/g) were excluded, and insulin, glucagon, and incretin levels, that might be modified by the enzymatic treatment, were not assessed." (PMID 25892991, 2015). "In the present study, we have further determined the effect of insulin on ADAM10 expression and activity in vitro and evaluated whether there are changes in ADAM10 level in type 1 diabetes and its role in determining levels of circulating soluble RAGE isoforms." (PMID 26325204, 2015).
type 1 diabetes (continued). "The immunological and genetic characterisation of patients with and without residual C-peptide may help to explain why some people with type 1 diabetes have enduring endogenous insulin secretion and some do not." (PMID 24121625, 2014). "Without adequate levels of insulin, individuals with type-1 diabetes may experience dangerous highs and lows in their blood sugar levels and must take insulin and sometimes other medications." (PMID 25407682, 2014). "Initial evidence for a role of Hsp60 in the progression of insulin-deficient/type 1 diabetes came from observations in the nonobese diabetic (NOD) mouse, an animal model of type 1 diabetes which shows aberrant Hsp60 expression in pancreatic beta cells already in the prediabetic phase." (PMID 24672802, 2014). "For instance, in the replacement of insulin-producing cells in patients with type-1 diabetes, there is little need for load-bearing structures, but rather for structures mimicking the extracellular matrix (ECM) like hydrogels, to retain and stimulate insulin-producing cells." (PMID 25520717, 2014). "The relationship between insulin and leptin has been heavily studied, with findings most recently suggesting that leptin has an inhibitory effect on insulin secretion and reduces glucagon secretion in rodents with type 1 diabetes, resulting in improved glycemic control in the absence of insulin." (PMID 24987413, 2014). "For example, people with type I diabetes in many LMIC die because of lack of insulin." (PMID 25348262, 2014). "However, since all type 1 diabetes patients need some type of long-acting insulin every day, insulin washout was not an option." (PMID 24739875, 2014). "The universal use of insulin could be a reason why overt hypertension is not commonly manifested early on in patients with type 1 diabetes." (PMID 24400109, 2014). "Youth with type 1 diabetes and public insurance have worse glycemic control and elevated CVD risk factors compared to those with private insurance, but this was no longer seen when insulin regimen was controlled for." (PMID 24955334, 2014). "A lack of insulin is speculated to exert a negative influence on bone formation resulting in a decreased peak bone mass in patients with type 1 diabetes, as the disease often starts at a time when peak bone mass is not yet achieved." (PMID 24721668, 2014). "However, human neutral protamine Hagedorn (NPH) insulin still remains the primary basal insulin choice, even though, recently, a randomized controlled trial demonstrated noninferiority of detemir versus NPH insulin in 310 pregnant women with type 1 diabetes." (PMID 23840206, 2013). "Globally Type I diabetes, an autoimmune disorder in which beta cells are not functional, affects 10% of diabetic population while 90% cases falls into category of Type II wherein down regulation of receptors leads to insulin non-responsiveness." (PMID 23822656, 2013). "None of the pregnant women with type 1 diabetes used insulin pump devices." (PMID 24319455, 2013). "Since insulin was recently demonstrated to suppress plasma arginase activity in diabetic patients, the reduction or lack of circulating insulin may contribute to the increase in arginase activity in type 1 diabetes." (PMID 23730303, 2013). "Values over this are consistent with short-term insulin independence in an individual who has not previously ‘failed’ non-insulin therapy, but may occur in the Type 1 diabetes honeymoon period." (PMID 23413806, 2013). "Insulin should never be stopped completely in patients with type 1 diabetes." (PMID 22943220, 2012). "This algorithm may be highly specific for finding patients with T2D (instead of type 1 diabetes), but would miss those patients who had progressed in disease severity such that oral hypoglycemic agents no longer worked and who now require insulin treatment." (PMID 23300414, 2012).
type 1 diabetes (continued). "An important argument against an involvement of LPL in insulin secretion is that insulin-dependent diabetes is not a commonly reported problem in animal models of LPL deficiency, or in patients with either total LPL deficiency or with non-functional LPL protein." (PMID 23186339, 2012). "Sufferers of type 1 diabetes require stringent monitoring of blood glucose levels and treatment with exogenous insulin administered through regular injections or through continuous monitoring insulin pumps, to replace the absent insulin." (PMID 22851965, 2012). "Expression of insulin in terminally differentiated non-beta cell types in the pancreas could be important to treating type-1 diabetes." (PMID 22242153, 2012). "The rationale for xenotransplantation is that the implanted porcine islets have the potential to mimic the normal physiological insulin response in type 1 diabetics, so that near-normal blood glucose levels are achievable without insulin administration or with a reduced requirement for it." (PMID 22384031, 2012). "Intensive insulin therapy using a basal-bolus approach, whether as multiple daily injections or pump therapy, is considered the best treatment for individuals with type 1 diabetes regardless of age." (PMID 20456170, 2010). "There are a number of barriers to glycaemic control in type 1 diabetes, including the occurrence and fear of hypoglycaemia and the complexity and demands of day-to-day management, in particular the need for frequent self-monitoring of blood glucose (SMBG) and regular adjustments in insulin dosing." (PMID 20456170, 2010). "The pathophysiology of type 1 diabetes (T1DM) is the result of the destruction of the insulin-producing beta cells, and a promising treatment paradigm for T1DM is replacement of the missing beta cells with insulin-producing cells derived from embryonic or other stem cell sources." (PMID 19742322, 2009). "Similarly, a case-only gene-gene interaction analysis between C883A and the known type 1 diabetes loci, HLA, INS, CTLA4 and PTPN22, revealed no consistent evidence of an interaction with C883A." (PMID 18045485, 2007). "Sincerepletion of the insulin deficiency that is presentin non-acidotic, ambulatory patients with newonset Type 1 diabetes did not alter serum leptin,these results argue against an effect of insulin onserum leptin in the absence of the acute diabeticketoacidosis." (PMID 12369715, 2001). "Thus, whereas type 1 diabetes is characterized by a complete lack of insulin production, type 2 is characterized by reduced insulin production plus insulin resistance." (PMID 15706798, 1998). "Type 1 Diabetes Mellitus (T1DM) is a chronic metabolic disorder of elevated blood glucose levels due to lack of insulin." (PMID 40346500, 2025). "However, if the glucose tolerance and insulin sensitivity are not damaged in the same time, for example in patients with type-1 diabetes, adrenal insufficiency or pancreatic β-cell dysfunction, these two experiments may present different results." (PMID 40015624, 2025). "In patients with type 1 diabetes (T1D), CIPII improves glucose control without increasing the risk of severe hypoglycemia, possibly through restoring the physiological porto-systemic insulin gradient." (PMID 40995084, 2025). "Type 1 diabetes mellitus (T1DM) is an autoimmune disease in which pancreatic β cells are destroyed, resulting in an absolute lack of insulin." (PMID 39544933, 2024). "Despite increasing use of continuous glucose monitoring (CGM) and continuous subcutaneous insulin infusion (CSII, insulin pumps) in type 1 diabetes (T1D) in pregnancy, achieving recommended pregnancy glycaemic targets (3.5–7.8 mmol/L or 63–140 mg/dL) remains challenging." (PMID 36927458, 2023).
type 1 diabetes (continued). "Here, we designed a novel clinical trial platform to test whether a short course of therapy with an agent known to have effects in type 1 diabetes with residual endogenous insulin could transiently induce insulin secretion in those who no longer produce insulin." (PMID 38096190, 2023). "Thus, the lack of insulin in type 1 diabetes could have impaired cardiac growth in adolescents with type 1 diabetes during development." (PMID 40303256, 2023). "Our work is the first to prove that additional insulin based on a modified FPU algorithm (200 kcal protein or fat equaling 10 g carbohydrates) can be safely administered before a high-fat, high-protein meal in adults with type-1 diabetes using MDI therapy without raising the risk of hypoglycemia." (PMID 37845717, 2023). "Type 1 diabetes (T1DM) is an autoimmune condition characterized by the lack of insulin production from the pancreas." (PMID 35808386, 2022). "The importance of SMBG in the management of type 1 diabetes mellitus (T1DM) patients is undeniable, and the link between increased SMBG frequency and decreased hemoglobin A1C levels (HbA1C) has been established, especially with those on insulin therapy." (PMID 35402120, 2022). "Insulin has long been considered to be a predominant and disease-initiating antigen in Type 1 Diabetes (T1D) in humans and in the non-obese diabetic (NOD) mouse model of autoimmune diabetes." (PMID 36032090, 2022). "Type 1 diabetes (T1D) is an autoimmune disease involving that the pancreatic islets produce little or no insulin." (PMID 36099285, 2022). "Among females with type 1 diabetes, exclusive and partial pump use may have the unintended consequence of increasing adiposity over time compared to exclusive use of injections, independent of insulin dose." (PMID 35127949, 2022). "However, while the use of SMBG in patients with type 1 diabetes (T1DM) has been associated with improved health outcomes, the evidence base for the impact of SMBG on patients with type 2 diabetes (T2DM), especially those not on insulin, has been conflicting." (PMID 34277218, 2021). "Intermittent use of FGM by T1DM patients can improve their HbA1c and glycaemic control without increasing the hypoglycaemic exposure in insulin-treated individuals with type 1 diabetes in an developing country." (PMID 34907285, 2021). "In type 1 diabetes (T1D), life-long insulin replacement is required to compensate for the practically nonexistent insulin secretion due to the autoimmune destruction of the pancreatic beta-cells." (PMID 35082757, 2021). "Moreover, when administered in combination with insulin, DS20060511 further enhanced glucose uptake into the skeletal muscle in both normal and insulin-resistant mice, and further reduced the blood glucose levels in a mouse model of STZ-induced type 1 diabetes." (PMID 34417555, 2021). "For instance, although STZ is toxic to pancreatic β-cells, reducing their numbers enough to lower circulating plasma insulin and raise blood glucose into the hyperglycemic range, some β-cells remain, unlike that observed in humans with long-standing type 1 diabetes." (PMID 33042003, 2020). "Interestingly, the use of an alternative start codon in human preproinsulin mRNA can lead to the translation of a nonconventional insulin product and the generation of neoantigenic peptides thereof, which are targets of T cell-mediated autoimmunity in type 1 diabetes." (PMID 32894308, 2020). "Therefore, liraglutide did not affect the insulin level in rats with type-1 diabetes." (PMID 33233692, 2020). "Many patients with type 1 diabetes (T1D) do not achieve the glycemic target goal with insulin treatment." (PMID 32973680, 2020). "However, acute treatment with liraglutide for 120 min at the highest dose reduced plasma insulin level in rats with type-1 diabetes to 1.98 ± 0.72 μU/mL (n = 6), which was not significantly different (p > 0.05) from that in vehicle-treated rats (2.21 ± 0.84 μU/mL; n = 6)." (PMID 33233692, 2020).
type 1 diabetes (continued). "In this study, a valid and reliable scale was developed in order to measure insulin treatment self-management of children with type 1 diabetes and their parents In addition, since there is no similar scale in the literature, it could be used in future studies on this issue." (PMID 30905141, 2019). "Without a diagnosis of type 1 diabetes, a patient will not receive appropriate education and will not be eligible for interventions that are often restricted to those with type 1 diabetes, such as carbohydrate counting, continuous glucose monitoring and insulin-pump therapy." (PMID 30969375, 2019). "Type 1 diabetes (T1D) is a chronic disease in which pancreas does not produce insulin, the hormone that stimulates transport of glucose from bloodstream to cells." (PMID 30922295, 2019). "Partial recovery of insulin production during the first year of diagnosis could substantially alter the treatment paradigm compared with the later stages in the course of type 1 diabetes, and our findings should not be applied beyond the first year of diagnosis." (PMID 30944112, 2019). "Sotagliflozin has been approved within the European Union for use as an adjunct to insulin therapy to improve glycemic control in adults with Type 1 diabetes and a body mass index ≥27 kg/m2, who could not achieve adequate glycemic control despite optimal insulin therapy." (PMID 31064765, 2019). "However, the α-cell response to hypoglycemia was not enhanced in insulin-treated, metformin-treated and in type 1 diabetes and thus the α-cell response to hypoglycemia may be unaltered or enhanced depending on the study population." (PMID 31781045, 2019). "However, no such reductions on exogenous insulin are seen in individuals with type 1 diabetes." (PMID 29342932, 2018). "Type 1 diabetes (T1D) is a chronic disease characterized by an increase in blood glucose due to a lack of insulin production." (PMID 29695241, 2018). "One study conducted in people with type 1 diabetes showed that compared to injection of insulin aspart into normal abdominal tissue, injection into lipohypertrophied tissue resulted in a 25% and 22% decrease in insulin Cmax and 4-hour insulin exposure (AUC0–4h), respectively." (PMID 30116732, 2018). "Indeed, a previous study showed that non-inbred BB rats (BB/Hagedorn; a model where lymphopenia is not present) displayed diminished release of insulin during stimulation with 20 mmol/l glucose in perfused whole pancreas at 50 days of age (before onset of type 1 diabetes)." (PMID 29209740, 2018). "Fifteen male individuals with type 1 diabetes (HbA1c 7.0% ± 0.6% (53 ± 7 mmol/mol)) underwent a 90 min iso-energetic continuous cycling session at 50% VO2max while ingesting combined glucose-fructose (GLUFRU) or glucose alone (GLU) to maintain stable glycaemia without insulin adjustment." (PMID 28230765, 2017). "Although there is evidence that metformin can limit insulin dose requirement, there is little evidence to support the recommendation by current guidelines that it can help to improve glucose control in individuals with type 1 diabetes who are overweight or obese." (PMID 28770327, 2017). "Another system for optimizing insulin infusion rates based on nonlinear model predictive control was designed using in silico data from a virtual type 1 diabetes patient, where the system was evaluated using data from a mathematical model of a patient with type 1 diabetes." (PMID 28812013, 2017). "Moreover, C646 increased AKT and GSK phosphorylation in the absence of insulin, suggesting that P300 acetyltransferase inhibitors may offer promise for the treatment of type 1 diabetes." (PMID 28743992, 2017). "Although, both provide night-time coverage, and insulin detemir’s shorter absorption profile may be compensated for by the intravascular albumin binding buffer erratic changes in insulin absorption, neither is a true 24-h insulin in people with type 1 diabetes." (PMID 28779138, 2017).